LRP12 (LDL receptor related protein 12)
Description:
Probable receptor, which may be involved in the internalization of lipophilic molecules and/or signal transduction. May act as a tumor suppressor.
Synonyms: ST7; FLJ12929; ALS28; MIG13A
Tractability: Antibody: its Gene Ontology location is reachable by antibodies, with high confidence; UniProt predicts a signal peptide or a membrane-spanning region; the Human Protein Atlas places it where antibodies can reach. PROTAC: ubiquitination databases record sites on it.
Gene: Protein-coding gene on chromosome 8 (104,489,231 to 104,589,258, reverse strand). Ensembl gene ENSG00000147650.
Subcellular location: Membrane; Membrane, coated pit
Subcellular location (Human Protein Atlas): Mitochondria; Nucleoli fibrillar center; Plasma membrane
Pathways (Reactome):
Sensory Perception: Retinoid metabolism and transport
Gene Ontology:
Molecular function: protein binding; low-density lipoprotein particle receptor activity; integrin binding
Biological process: neuron migration; neuron projection development; endocytosis; regulation of growth; signal transduction
Cellular component: plasma membrane; membrane
Genetic constraint (gnomAD): Loss-of-function variants: 14 observed, 75.25 expected, observed/expected ratio (o/e) 0.19, 90% interval 0.12 to 0.29. The upper end of that interval is the gene's LOEUF score, 0.29, which puts it in group 1 of 6, group 1 being the genes least tolerant of losing a copy. Missense variants: 863 observed, 1,083.2 expected, observed/expected ratio (o/e) 0.8, 90% interval 0.75 to 0.84. Synonymous variants: 349 observed, 370.39 expected, observed/expected ratio (o/e) 0.94, 90% interval 0.86 to 1.03.
Gene-disease validity (ClinGen):
ClinGen rates the evidence that LRP12 causes each of these diseases.
oculopharyngodistal myopathy 1 (autosomal dominant): Moderate.
Homologues: Orthologues: chimpanzee LRP12 (99% identical), macaque LRP12 (99% identical), rabbit LRP12 (95% identical), dog LRP12 (95% identical), pig LRP12 (94% identical), mouse Lrp12 (93% identical), rat Lrp12 (92% identical), tropical clawed frog lrp12 (77% identical), guinea pig LRP12 (76% identical), zebrafish lrp12 (72% identical), Drosophila melanogaster arr (6% identical). Paralogues in human: LRP3 (39% identical), LRP10 (30% identical), LRP1 (22% identical), LRP1B (22% identical), LRP2 (19% identical), VLDLR (16% identical), LRP8 (15% identical), LRP4 (12% identical), NID2 (12% identical), NID1 (12% identical), EGF (11% identical), and 2 more.
Diseases named in the same sentence as LRP12 in open-access papers:
LRP12 is named in the same sentence as 33 diseases in open-access papers, as found by Europe PMC text mining. Sharing a sentence is not in itself a finding about the gene and the disease. The quoted sentences say what the papers report.
oculopharyngodistal myopathy (4 papers, 2022 to 2025). Oculopharyngodistal myopathy (OPDM) is a rare, adult-onset hereditary muscle disease. "Oculopharyngodistal myopathy (OPDM) is a group of disorders caused by mutations in several genes such as LRP12, GIPC1, NOTCH2NLC and RILPL1." (PMID 39501809, 2024). "The expansion of several other CGG repeats located in 5’ UTRs have been implicated in oculopharyngodistal myopathy (OPDM): NOTCH2NLC, GIPC1, LRP12, RILPL1, and ABCD3." (PMID 39868092, 2025). "These include NOTCH2NLC repeat expansion in NIID and intronic CCG repeat expansions in NUTM2B-AS1, LRP12 and GIPC1 causing oculopharyngeal myopathy with leukoencephalopathy, oculopharyngodistal myopathy (OPDM) types 1 and 2, respectively." (PMID 39349043, 2025).
Obesity (3 papers, 2022 to 2025). Accumulation of substantial excess body fat. "Of them, Ctnnd2, Dap, Marchf6, Cmbl, Sdc2, Cpq, Stk3, Vps13b, Cox6c, Grhl2, Fzd6, Cthrc1, Lrp12, and Zfpm2 showed associations or had functions related to atherosclerosis or obesity." (PMID 40362477, 2025). "Low-density lipoprotein receptor–related protein 12 (LRP12: 34.3%-58.1%) and coagulation factor (F)XI (20.6%-39.6%) mediated most of the associations between 3 obesity indicators and VTE." (PMID 38029854, 2024). "BMI in our studied population showed a direct relationship with the transcriptional changes (downregulated) observed on selected genes (APC, ARNT, CYP2D6, LEPR, LRP12, and MYC), all of which are closely linked to the development of cancer or obesity." (PMID 35420343, 2022). "Thirty of 38 combinations were related to obesity indicators, and 5 proteins (annexin II [Annexin A2], coagulation FXI, Kininostatin-1, LRP12, and prekallikrein [plasma kallikrein]) showed consistent mediation effects on the associations of 3 obesity indicators with VTE risk." (PMID 38029854, 2024).
acute myeloid leukemia (2 papers, 2022 to 2023). Acute myeloid leukemia (AML) is a group of neoplasms arising from precursor cells committed to the myeloid cell-line differentiation. "pointed out that LRP12 is closely related to acute myeloid leukemia." (PMID 38283345, 2023). "HL-60 was studied and characterized previously for Acute myeloid leukemia studies and the expression of pattern of CD109 and LRP12 could confirm its validation." (PMID 36299526, 2022).
B cell lymphoma (2 papers, 2014 to 2018). "The gene promoters of BMPER, CDH1 and LRP12 were methylated in all analyzed B-cell lymphoma cell lines across all subtypes." (PMID 25226156, 2014). "LRP12 (LDL receptor-related protein 12) encodes a transmembrane protein that is differentially expressed in many cancer cells and that has recently been shown to be frequently hypermethylated in B cell lymphoma." (PMID 30029672, 2018). "We focused on major types of B-cell lymphoma (BL, DLBCL ABC, DLBCL GCB, FL and PMBL) and demonstrated that the gene promoters of LRP12 (94%), CDH1 (92%), and BMPER (58%) were methylated at a high frequency, whereas DUSP4 and BMP7 showed lower methylation frequencies (32% and 22%, respectively)." (PMID 25226156, 2014).
lung carcinoma (2 papers, 2018 to 2020). "Next urgent steps include an integration of the LRP12 epigenetic test into the Network Genomic Medicine (NGM) Lung Cancer platform, Europe’s largest platform for molecular testing, to improve the accuracy of the prediction of platin therapy resistance and a transfer into clinical applications." (PMID 30029672, 2018).
oculopharyngodistal myopathy 1 (2 papers, 2022 to 2024). "LRP12 encoded protein is associated with Oculopharyngodistal Myopathy 1 and Neuronal Intranuclear Inclusion Disease." (PMID 36271373, 2022).
coronary artery disease (1 paper, 2016). "One of the loci for week 1 FS near Lrp12 and Zfpm2 on chromosome 15 has previously been shown in a small human GWAS to be associated with sudden cardiac arrest due to ventricular tachycardia and ventricular fibrillation in patients with coronary artery disease (p-value = 1 x 10−6)." (PMID 27385019, 2016).
glaucoma (1 paper, 2012). Increased pressure in the eyeball due to obstruction of the outflow of aqueous humor. "The LRP12 gene is a member of the LRP (low-lipoprotein receptor) gene family, with several members previously implicated in glaucoma." (PMID 22570617, 2012). "Using RT-PCR, we found that both LRP12 and ZFPM2 are expressed in the human optic nerve, as well as in other ocular tissues relevant to glaucoma." (PMID 22570617, 2012).
glioma (1 paper, 2021). A benign or malignant brain and spinal cord tumor that arises from glial cells (astrocytes, oligodendrocytes, ependymal cells). "GP130, low-density lipoprotein receptor-related protein 12 (LRP12), and Rap1 interacting factor 1 (RIF1), as candidate palmitoylated proteins for experimental validation, may be associated with glioma development and malignant progression." (PMID 33541421, 2021).
Immunodeficiency (1 paper, 2015). Failure of the immune system to protect the body adequately from infection, due to the absence or insufficiency of some component process or substance. "Recently, LRP12 mutations were found in patients with intestinal amyloidosis and CVID, which denotes the complex association between immunodeficiency and autoinflammatory disease." (PMID 26351592, 2015).
lung adenocarcinoma (1 paper, 2018). A carcinoma that arises from the lung and is characterized by the presence of malignant glandular epithelial cells. "Similarly, we find a shorter survival time for patients with LRP12 hypermethylation in the TCGA data set for NSCLC (lung adenocarcinoma)." (PMID 30029672, 2018).
lymphoma (1 paper, 2014). A malignant (clonal) proliferation of B- lymphocytes or T- lymphocytes which involves the lymph nodes, bone marrow and/or extranodal sites. "For BMPER, CDH1 and LRP12 statistically significant differences in the PMR values were seen between several of the lymphoma groups analyzed, as well as in comparison with the control samples." (PMID 25226156, 2014). "Taken together, we identified several genes (BMPER, BMP7, CDH1, DUSP4 and LRP12) which were frequently methylated in major lymphoma types." (PMID 25226156, 2014). "In a future perspective, the hypermethylated CDH1 and LRP12 gene promoters could be used in a blood-based test to differentiate lymphoma patients from healthy donors and follicular hyperplasia." (PMID 25226156, 2014). "However, to the best of our knowledge, this is the first time BMPER, BMP7, DUSP4 and LRP12 are reported to be methylated in lymphoma." (PMID 25226156, 2014). "The lymphoma patients included in the test series showed methylation frequencies of 93%, 90% and 60% for CDH1, LRP12 and BMPER, respectively." (PMID 25226156, 2014). "The promoter methylation of LRP12, CDH1, BMPER and DUSP4 was 100%, 91%, 55%, and 32% across all analyzed lymphoma types included in the validation series, respectively." (PMID 25226156, 2014). "The LRP12 and CDH1 genes have a great potential as DNA methylation biomarkers for lymphoma, since these were able to discriminate with a high sensitivity and specificity lymphoma patients from the various control samples and follicular hyperplasia." (PMID 25226156, 2014). "The combination of LRP12 and CDH1 methylation could successfully discriminate between the vast majority of the lymphoma and control samples, emphasized by receiver operating characteristic analysis with a c-statistic of 0.999." (PMID 25226156, 2014).
oral cancer (1 paper, 2017). "The rationale of choosing these CNA associated genes was basically due to LRP12, TPM2, EGFR, CCND1 being matched with ICGC and TCGA databases whereas FSCN1, CLPTM1L, CHL1 and CSMD1 had been found to be associated with oral cancer." (PMID 28384287, 2017). "This genetic signature marker contains LRP12, CCND1, EGFR and TPM2 genes that could predict clinical outcomes and facilitate selection of therapeutic strategies in oral cancer management that are tailor-made for patients." (PMID 28384287, 2017).
tumor (3 papers, 2018 to 2024). "With the exception of tumor 2, all tumor samples showed characteristic mutations of HNSCC including amplification of 3q26.2 (TP63, SOX2, PIK3CA), 5q14.3 (APC), 8q24.3 (PTK2), 8q22.3 (LRP12) as well as loss and/or LOH of 9p21.3 (CDKN2A)." (PMID 32426287, 2020). "We identified LRP12 as a resistance biomarker in the PDX models and further validated the methylation differences of responders and non-responders in an independent cohort with single-locus methylation analyses in 35 additional formalin-fixed and paraffin-embedded (FFPE) primary tumor samples." (PMID 30029672, 2018).
cardiovascular diseases (1 paper, 2024). "Genetically predicted levels of LRP12, prothrombin, angiopoietin-1 (ANGPT1), and low-density lipoprotein receptor–related protein 4 (LRP4) were positively associated with VTE and 3 cardiovascular diseases." (PMID 38029854, 2024).
peripheral nervous system disorder (1 paper, 2023). A disease involving the peripheral nervous system. "Interestingly, the gene LRP12 is involved in the internalization of lipophilic molecules, and FGD4 is known to cause a peripheral nervous system disorder (Charcot–Marie–Tooth disease)." (PMID 37144689, 2023).
LRP12 also shares sentences with these, for which no sentence is quoted: cancer (3 papers); Alzheimer disease (1); atherosclerosis (1); Charcot-Marie-Tooth disease (1); fragile X syndrome (1); gastric cancer (1); lymphoid leukemia (1); melanoma (1); neuronal intranuclear inclusion disease (1); non-small cell lung carcinoma (1); oral squamous cell carcinoma (1); ptosis (1); respiratory diseases (1); sudden cardiac arrest (1); vacuolar myopathies (1); ventricular fibrillation (1); ventricular tachycardia (1).